CTLA4 (cytotoxic T-lymphocyte associated protein 4)
Diseases named in the same sentence as CTLA4 in open-access papers (continued):
Sharing a sentence is not in itself a finding about the gene and the disease.
melanoma (continued). "Ipilimumab [commercialized anti-cytotoxic T-lymphocyte antigen-4 (anti-CTLA-4)] was the first approved ICI for treating patients with advanced melanoma." (PMID 34858835, 2021). "Among melanoma tumors, the biomarkers PD-L1, PD-L2 and CTLA-4 and those of “Effector molecule” category, such as Expanded immune signature and T cell-inflamed GEP, were significantly associated with favorable outcomes." (PMID 33915876, 2021). "Melanoma and UC shared the largest number of biomarkers correlated with response, including PD-1, PD-L1, PD-L2, CTLA-4, gene.CD8, all biomarkers of “Effector molecule”, APM and IS." (PMID 33915876, 2021). "Severe hypothyroidism has been reported in melanoma patients with anti-CTLA4 treatment but is uncommon (~1%)." (PMID 35154081, 2021). "Activation of CD8 T-cells by α4-1BB along with the expansion of CD4 effector T-cells by anti-CTLA-4 obviously suggested the noticed synergy between these agents to reject B16 melanomas." (PMID 34267616, 2021). "Although anti-CTLA4 treatment allowed to the overall survival of melanoma to be reached, with even cure of metastatic disease, for about 20% of the patients, nevertheless clinical application is limited because of its AIEs." (PMID 33800368, 2021). "Blockage of CTLA-4, either alone or in combinatorial treatments, has proven to be highly successful in tumors like melanoma and renal cell carcinoma." (PMID 34298735, 2021). "Anti-CTLA-4 (ipilimumab) plus anti-PD-1 (nivolumab) treatments are combinations approved for the treatment of melanoma, renal cell carcinoma, colorectal cancer, non-small cell lung cancer, hepatocellular carcinoma and pleural mesothelioma." (PMID 34680282, 2021). ") of 53 melanoma cases, there were 5 biopsy timepoints: pre-anti-CTLA4, on-anti-CTLA4, pre-anti-PD-1, on-anti-PD-1 and prog-anti-PD-1." (PMID 34344410, 2021). "In mouse melanoma models, tumor-intrinsic active β-catenin signaling results in T-cell exclusion and resistance to combination of anti-PD-L1 and anti-CTLA-4 mAbs." (PMID 34774008, 2021). "Previous studies have investigated higher membrane-bound CTLA-4 (mCTLA-4) expression was found in patients with melanoma, chronic myelomonocytic leukemia, and acute myeloid leukemia." (PMID 34006227, 2021). "For example, Zingg at al. observed that anti-CTLA-4 or IL-2 immunotherapy leads to TNFα amplification and T cell infiltration, resulting in EZH2 overexpression and loss of tumor control in melanoma mouse models." (PMID 34575678, 2021). "In the phase 3 KEYNOTE-006 trial, pembrolizumab as a single agent in melanoma patients previously untreated for their advanced or metastatic disease was investigated compared to anti-CTLA-4 ipilimumab therapy." (PMID 33804800, 2021). "Upon ipilimumab (anti-CTLA-4 blocking antibody) treatment in melanoma patients, a significant decrease in NK cell, ILC1 and ILC2 frequencies has been observed, associated with reduced expression of the inhibitory receptor CD96." (PMID 34885076, 2021). "Clinical trials in advanced melanoma patients treated with an antibody against the checkpoint inhibitor (CPI) CTLA-4 (ipilimumab) demonstrated significantly prolonged survival; more than ten years after treatment in some patients." (PMID 34830973, 2021). "In contrast, elderly melanoma patients seemed to have lower CTLA-4 (p=0.001) and PD-1 (p=0.033) expression than young patients." (PMID 33936087, 2021). "We found that the tumor-infiltrating lymphocytes decrease their expression of PD1 and CTLA-4, possibly indicating that these cells are “less exhausted” within the melanoma microenvironment after sensory hyperactivation." (PMID 34784974, 2021). "Consistent with this, CTLA-4 overexpression on tumor-infiltrating lymphocytes has been considered as a red flag for melanoma patients [hazard ratio (HR): 7.962, 95% CI: 1.832–34.598, P-value = 0.006]." (PMID 33692796, 2021).
melanoma (continued). "PsP was first described on immunotherapy of the CTLA-4 inhibitor in melanoma, with a patient who experienced an enlargement of a cutaneous lesion after initial treatment, followed by a long-term stability." (PMID 34733781, 2021). "To further test the clinical relevance of Sunitinib‐mediated inhibition of tumor PD‐L1 and subsequent immune surveillance, we utilized combination therapeutic strategy by cotreating Sunitinib and CTLA‐4 mAb in both melanoma and NSCLC immune competent mice." (PMID 33510997, 2021). "In opposite, in challenging B16 melanoma model, the tumor progressively developed in mice which were treated with anti-4-1BB mAb or anti-CTLA-4 monotherapy." (PMID 34267616, 2021). "Greater local control with anti-PD-1 versus anti-CTLA-4 was observed in cerebral metastases from melanoma patients." (PMID 34769050, 2021). "With the recent findings of tumor CTLA-4 and PD-1 expression on melanoma, the cross-talk between the CTLA-4/PD-1 and MAPK-PI3K/AKT signaling pathways deserves further investigation." (PMID 33692796, 2021). "This has been observed in patients with melanoma receiving anti–CTLA-4 therapy as well as patients with RCC." (PMID 34046341, 2021). "The anti-CTLA4–PD-1 dual immunotherapy has been successful in the treatment of a set of tumors including melanoma." (PMID 34040608, 2021). "The very first FDA-approved checkpoint inhibition immunotherapy employed ipilimumab (Yervoy®), a CTLA-4 monoclonal antibody (mAb), to treat melanoma by blocking the CTLA-4 pathway." (PMID 33668746, 2021). "Immune checkpoint inhibitors (ICI), such as anti-programmed death-1 (PD-1) and anti-cytotoxic T-lymphocyte-associated antigen 4 (CTLA-4) antibodies, have shown widespread effectiveness in treating many cancers particularly malignant melanoma." (PMID 34345559, 2021). "These cytokines were profiled longitudinally in 98 melanoma patients receiving mono-immunotherapy with anti-PD-1 and validated on 49 patients receiving combo immunotherapy with anti-PD-1 and anti-CTLA-4." (PMID 35008245, 2021). "CTLA4 is expressed in immune cell malignancies including leukemic B cells and also by breast cancer cells, melanoma, and various carcinomas." (PMID 35154081, 2021). "Currently, three immune checkpoint inhibitors (ICIs) are approved for the treatment of stage IV melanoma: the anti-CTLA4 antibody ipilimumab, and the anti-PD1 antibodies nivolumab and pembrolizumab." (PMID 34885249, 2021). "Ipilimumab (IgG1 mAb) is an approved ICI drug of the anti-CTLA4 antibody to be used as a treatment of advanced melanoma and has demonstrated a significant and long-lasting effect in approximately 15 to 20% of treated patients." (PMID 34869309, 2021). "Because CTLA-4 inhibition results in increased activation of the immune system, Ipilimumab, an inhibitor of CTLA-4, was approved for the treatment of advanced or unresectable melanoma." (PMID 34526987, 2021). "A study utilizing the B16-OVA mouse melanoma model demonstrated that the anti-tumor effect of an IL-2/anti-IL-2 complex combined with anti-CTLA-4 mAbs was dependent on both NK cells and CD8+ T cells." (PMID 34503073, 2021). "The expert panel the results of the Phase II clinical trial of 227 patients with advanced melanoma treated with CTLA-4 inhibitor (Ipilimumab) agent and defined a new response assessment criteria, the irRC that they developed from WHO criteria." (PMID 33625595, 2021). "Meanwhile, the impact of the statuses of PD-L2, TIS, IFN-gamma, T cell-inflamed GEP, AMP and IRP on objective response was also observed in melanoma patients with combination anti-PD-1 and anti-CTLA-4 immunotherapy." (PMID 33915876, 2021). "Similar to PD-L1, the expression of CTLA-4 in human melanoma cells is also regulated by IFN-γ through the JAK1/2-STAT1-IRF1 pathway." (PMID 34620200, 2021). "Monoclonal antibodies against the checkpoint molecules PD-1 and CTLA-4 have shown early clinical success against melanoma and are now approved to treat various cancers." (PMID 34503073, 2021).
melanoma (continued). "In 2011, ipilimumab was the first immunotherapy drug targeting CTLA-4 to receive FDA approval to treat late-stage melanoma." (PMID 33809974, 2021). "Ipilimumab, the inhibitor of CTLA-4, and nivolumab and pembrolizumab, both PD-1 inhibitors, were approved originally for the treatment of advanced melanoma and resected disease as monotherapy." (PMID 34830947, 2021). "Further, the TIR signature can predict the response of melanoma patients to anti-CTLA4 therapy and their survival outcome, with higher accuracy than other biomarkers." (PMID 33753855, 2021). "In a melanoma model, CTLA-4 blockade increased CD8+ T cell motility within the tumor, which enhanced the brief contact with a large number of tumor cells, and the killing efficiency." (PMID 34572844, 2021). "Immune check-point therapy based on cytotoxic T lymphocyte-associated antigen 4 (CTLA4), programmed death-1 (PD-1), and programmed death ligand-1 (PD-L1) inhibitors has a good effect in non–small-cell lung carcinoma and melanoma." (PMID 33928028, 2021). "For example, the three-year overall survival rates for melanoma patients receiving combination therapy, anti-PD-1, and anti-CTLA-4, were 58%, 52%, and 34%, respectively." (PMID 34638308, 2021). "And in October 2015, the FDA approved a melanoma regimen that combines anti-CTLA-4 (ipilimumab) with anti-PD1 (nivolumab)." (PMID 33716732, 2021). "From a clinical standpoint, immune checkpoint therapy (ICT) has significantly improved the outcome for melanoma patients, and numerous studies have demonstrated that expression of PD-1/PD-L1 and CTLA4 are often predictors for efficacy of immunotherapy." (PMID 33649199, 2021). "According to the subgroup analysis, we found that great heterogeneity in 1st line (p < 0.00001, I2 = 89%), anti-CTLA-4 (control group) (p = 0.008, I2 = 71%), melanoma (p < 0.00001, I2 = 89%), head and neck squamous cell carcinoma (p =0.05, I2 = 73%) groups." (PMID 33531977, 2021). "Immune checkpoint blockade (ICB) therapy targeting PD-1 and CTLA-4 as single or combined therapy has revolutionized the treatment of patients with several cancer types including melanoma." (PMID 34187852, 2021). "This population was characterized by a Th1 effector memory profile in mice and was also identified in peripheral blood of melanoma patients responding to anti-CTLA-4 antibodies in combination with granulocyte-macrophage colony-stimulating factor (GM-CSF)." (PMID 34064410, 2021). "Further supporting that notion, we did not observe improved control of larger tumors in the B16, BP or D4M-UV2 melanoma models by the combination of AZD1152 combined with anti-CTLA4 or anti-PD1." (PMID 33123754, 2021). "The effector Tregs are highly activated and proliferative with high CTLA-4 expression (FOXP3++CD25++CD45RA−CTLA4+++) in melanoma." (PMID 34806028, 2021). "The combination of Azacytidine and CTLA-4 blocking antibodies showed combinatory effects in the B16-F10 melanoma model." (PMID 33859645, 2021). "For this study, one group of mice bearing subcutaneous B16GP33 melanoma tumors were administered two doses of CTLA-4 monoclonal antibody prior to histotripsy and an additional treatment afterwards." (PMID 34136405, 2021). "Combination of anti-RANKL and anti-CTLA4 antibody therapy enhanced anti-tumor response and survival after melanoma challenge." (PMID 34899700, 2021). "We also identified that conditional knockout of Casp8 in NK cells caused a reduction in IFN‐γ and CD107a secretion and an increase in PD‐1 and CTLA‐4 expression, thereby promoting tumor growth of melanoma cells in Ncr1iCre/+Casp8fl/fl mice." (PMID 33934451, 2021). "Antitumor effects of anti-cytotoxic T lymphocyte antigen (CTLA)-4 blockade in melanoma depend on distinct Bacteroides species." (PMID 34206200, 2021). "Blockade of CTLA4 has proven effective in melanoma and other tumors, and has a profound effect on the Treg population." (PMID 33520112, 2021).
melanoma (continued). "Relative lymphocyte count (RLC) and relative eosinophil count (REC) were also evaluated by the same group in advanced melanoma patients receiving chemotherapy (n = 116) or anti-CTLA-4 therapy (n = 128)." (PMID 35008245, 2021). "For example, TMB-high was associated with a survival benefit for metastasized or unresectable melanoma patients with ipilimumab (anti-CTLA-4) and nivolumab (anti-PD-1) therapy." (PMID 34221994, 2021). "Ipilimumab is an anti-CTLA-4 antibody, it is used for treatment of patients with advanced-stage melanoma." (PMID 33494227, 2021). "Combination treatment of both anti-PD-1 and anti-CTLA4 antibodies resulted in a more severe hepatotoxicity: 17.6–21% for all grades and 8.3–11% for grade 3/4 toxicity in patients treated for melanoma." (PMID 33494227, 2021). "Preclinical research has demonstrated that EZH2 inhibition synergizes with anti-CTLA-4 in mouse melanoma models, where EZH2 inhibition restored melanoma immunogenicity and antigen presentation." (PMID 34944799, 2021). "Combinations of PD-1/PD-L1 axis inhibitors with inhibitors of cytotoxic T-lymphocyte-associated protein 4 (CTLA-4) have also been studied, and are now widely used for melanoma, renal cell carcinoma (RCC), and non-small cell lung cancer." (PMID 33804039, 2021). "For instance, treatment‐associated increases in serum Ang2 appeared to predict reduced OS and reduced responses to CTLA‐4/PD‐1 blockade in patients with advanced melanoma." (PMID 34125494, 2021). "Results were consistent in the subgroups of patients treated with anti-CTLA-4 or anti-PD(L)-1, and in subgroups of patients treated for melanoma or pulmonary cancer." (PMID 34068892, 2021). "In fact, clinical studies of combination therapies of anti-PD-1 (nivolumab) or anti-CTLA-4 (ipilimumab) with cancer vaccines provided improved response rates in melanoma and pancreatic adenocarcinoma compared with anti-PD-1 or anti-CTLA-4 alone." (PMID 34065346, 2021). "PRJEB23709 included 158 tumor biopsies from 120 melanoma patients treated with anti-PD-1 monotherapy (nivolumab or pembrolizumab) or combined anti-PD-1 and anti-CTLA-4 (nivolumab or pembrolizumab combined with ipilimumab)." (PMID 33922038, 2021). "The inhibition of CTLA-4 expression with the monoclonal antibody ipilimumab reverses immune suppression and promotes a significant anti-cancer response in melanoma." (PMID 34178688, 2021). "In this study, therapeutic response was shown to correlate with an increase in clonality of the TCR repertoire in ipilimumab naïve melanoma patients, whilst correlating instead with an increase in its richness in patients pre-exposed to the anti-CTLA-4." (PMID 33602280, 2021). "It has been shown recently that neoantigen load is an important predictor of responses to anti-CTLA-4 therapy; high neoantigen loads in melanoma are correlated with favorable responses to anti-CTLA-4 therapy." (PMID 33547395, 2021). "Melanoma is known to evade the immune system by increasing expression of PD-L1 (ligand for the T cell PD-1 receptor) on melanoma cells and CTLA-4 (an immune suppressive protein) on T cells." (PMID 35008286, 2021). "Similar findings were observed in another cohort of melanoma patients (n = 42) treated with anti-CTLA-4 therapy." (PMID 35003141, 2021). "Ipilimumab, a monoclonal antibody against CTLA-4, was the first drug to demonstrate a significant improvement in OS of advanced melanoma in a phase 3 study." (PMID 33804800, 2021). "Immune checkpoint inhibitors, such as ipilimumab (monoclonal antibody to CTLA4) and nivolumab (monoclonal antibody to PD-1), have demonstrated survival benefits in multiple tumor types, including melanoma, non-small cell lung cancer, and renal cell carcinoma." (PMID 33710817, 2021). "We analyzed the same correlations in a publicly available dataset of patient-derived melanoma samples obtained before or after initiation of anti-CTLA4 treatment." (PMID 33123754, 2021).
melanoma (continued). "More recent treatment modalities including targeted treatment and checkpoint inhibitor treatment addressing CTLA-4 and PD-1 signaling in immune cells have improved the overall survival of melanoma patients." (PMID 34281234, 2021). "Patients with high m6Sig score exhibited significantly longer survival time (log-rank test, p = 0.0082) and markedly clinical response to PD-1/CTLA-4 treatment in melanoma (response rate, high vs low m6Sig score subgroup, 52.3 vs 31.2%)." (PMID 34993195, 2021). "The lack of T cell infiltration and activation of the WNT/β-catenin pathway was involved in the resistance to anti-PD-L1/anti-CTLA-4 antibody therapy in a melanoma mouse model." (PMID 34827646, 2021). "In melanoma cells, the tumoral expression of CTLA-4 can maintain the stem cell feature of melanoma and confer anti-apoptotic features to the tumor." (PMID 33692796, 2021). "In 2010, ipilimumab (a monoclonal antibody targeted to CTLA-4) was shown to provide clinical benefit in cancer patients (melanoma and other tumors), extending median overall survival (OS) to 10 months." (PMID 34830221, 2021). "Some solid tumors, including melanoma, exploit this CTLA-4-mediated T cell inhibition to create a favorable environment for their progression." (PMID 34356899, 2021). "Compared with standard anti-CTLA4 monotherapy, anti-CTLA4-TβR II molecules show more robust antitumor activity in human melanoma mouse models." (PMID 34335834, 2021). "Clinical studies using patient samples have correlated CTLA-4 expression of tumor-infiltrating T cells to ipilimumab response in melanoma using whole-exome RNA sequencing, and in NSCLC patients through IHC staining of tumor sections 132,133." (PMID 33391977, 2021). "Ipilimumab, an mAb that targets CTLA-4, was approved as a checkpoint inhibitor for the treatment of advanced melanoma in 2011." (PMID 33801815, 2021). "As well as Ipilimumab, as an inhibitor of cytotoxic T lymphocyte-associated antigen-4 (CTLA-4), has been proved to be valid in treating melanoma and lung cancer." (PMID 33345275, 2021). "Four articles including 68 patients were available of CRR of melanoma after neoadjuvant therapy, two of which combined PD‐1/PD‐L1 inhibitors and CTLA‐4 inhibitors in the neoadjuvant therapy, and the rest used PD‐1/PD‐L1 inhibitors monotherapy." (PMID 34766136, 2021). "Clinical trials in melanoma patients that have combined PD-1 and CTLA-4 blockade have shown improved clinical responses, however, these have come at a cost with an increase in toxicities being reported." (PMID 33859638, 2021). "The clinical success of anti-CTLA4 ICIs was observed in advanced melanoma through the use of ipilimumab, a fully humanised antibody anti-CTLA4 monoclonal antibody (IgG) isolated from transgenic mice and produced from a hybridoma clone." (PMID 33921181, 2021). "We have previously shown that CTLA4 promoter methylation inversely correlates with its corresponding mRNA expression (Spearman’s ρ = – 0.42, P < 0.001) in a large melanoma cohort from The Cancer Genome Atlas." (PMID 33196890, 2021). "In mouse models of melanoma brain metastasis, the combination of axitinib with anti-CTLA-4 antibodies increases the number of effector T-cells and antigen presentation by dendritic cells, which promotes a reduction on tumor growth and an increase in OS." (PMID 33916438, 2021). "Apart from AZA and DAC, another DHA—guadecitabine—increases the level of Ctla4 in melanoma and hematological cancer cells." (PMID 34281195, 2021). "The combination of DC based vaccines with immune checkpoint blockers (anti-CTLA-4 and anti-PD-1/PD-L1) showed an improved targeting and a successful eradication of CSCs in melanoma, GBM and bladder cancer models." (PMID 34572009, 2021). "Recent studies show that CTLA-4 expression was overactivated in several malignant tumors, such as melanoma and spinal chordoma." (PMID 34526987, 2021).